TNF (tumor necrosis factor)
Diseases named in the same sentence as TNF in open-access papers (continued):
Sharing a sentence is not in itself a finding about the gene and the disease.
tumor (continued). "β2AR signaling can also polarize macrophages from M1 to M2 type, thereby enhancing anti-inflammatory cytokines like IL-10, IL-4 & IL-13, and decreasing pro-inflammatory cytokines like INFγ, TNFα, IL1β, CCL2, CCL3 and CCL4 to cause tumor progression." (PMID 37006295, 2023). "The number of cells that were positive for the expression of CD8 and NKp46/NCR1 was significantly increased in the anti-TNFα mAb group, indicating that immunity against the tumor was enhanced in the anti-TNFα mAb group." (PMID 36996146, 2023). "And it was shown that upregulation of albumin promotes tumor proliferation and metastasis via activating expression of tumor necrosis factor-α, interleukin-1, and interleukin-6." (PMID 37251954, 2023). "Theragnostic biomarkers like IDO1, s-CTLA-4, IFN-γ, TNF-α and IL-2 have been studied in various tumors, and seems to hold significant potential in mapping the tumor microenvironment and predicting response to ICPIs." (PMID 36879122, 2023). "TNF was first identified for its capacity to induce tumor necrosis and to promote endothelial cell death." (PMID 38139369, 2023). "PANoptosis kills cancer cells and inhibits tumor growth by inducing cell death through TNF-α and IFN-γ, thus contributing to the treatment and intervention of cancer." (PMID 37415742, 2023). "M1 macrophages mainly induce the production of pro-inflammatory cytokines such as TNF-α, IL-1β, IL-6, and IL-12, which are conducive to anti-tumor effects." (PMID 37758759, 2023). "Z. multiflora essential oil (500 mg/kg) reduced tumour weight and balanced T helper 1 levels by increasing the secretion of TNF‐α, Interferon‐gamma (IFN‐γ) and IL‐2 and decreasing IL‐4 levels." (PMID 37697969, 2023). "Tumor cell senescence can be induced in vitro following combined exposure to TNF-α and IFN-γ, two cytokines that are endogenously produced by tumor-infiltrating Th1 helper lymphocytes." (PMID 37566008, 2023). "Early clinical trials have shown that fourth-generation CAR-T cells secreting IL-12 resulted in apoptosis and elimination of suppressive CD4+CD25+Foxp3+ Tregs in addition to the activation of TNFα producing Mφs, both of which contributed to tumour elimination." (PMID 39935547, 2023). "IL-1β and tumor necrosis factor (TNF)-β reportedly contribute to forming the cold tumor immune microenvironment by suppressing TILs." (PMID 37686634, 2023). "T‐cell exhaustion, one of the contributors to tumor immune escape is characterized by reduced levels of TNF‐α and IFN‐γ and impaired CD8+ T cell cytotoxicity." (PMID 37506147, 2023). "The capacity of TRM cells to secrete IFN-γ and TNF-α provides evidence for a key role of these cells in antitumor immune responses and in the control of tumor progression in melanoma." (PMID 37545498, 2023). "Vascular responses such as changes in barrier function were studied in inflamed HUVEC (exposed to 2.25 ng/ml TNFα) as well as in presence of a PDAC tumor compartment." (PMID 37205118, 2023). "They observed that WGP increased the production of TNF-α in lung interstitial macrophages and enhanced their phagocytic capacity and cytotoxicity to tumor cells." (PMID 37069227, 2023). "The inhibitory activity of PP2A by overexpression of SET and CIP2A increases hyper-phosphorylated proteins, including pS62-MYC and pAkt, and induces proinflammatory cytokines TNF-α and IL-1, which are presented as essential molecules in tumor promotion." (PMID 37097392, 2023). "TNF-α is a small molecular protein produced by activated white blood cells, which can promote phagocytosis of granulocytes, inhibit and kill tumor cells, promote cell proliferation and differentiation, and is an important inflammatory factor." (PMID 37756110, 2023). "Omeprazole and pantoprazole have been already proved to decrease pro‐inflammatory factors such as TNF and IL‐6, and increase anti‐inflammatory factors such as IL‐10 implying the potential for anti‐tumour." (PMID 35961680, 2023).
tumor (continued). "These experiments demonstrate that human TNF-α is a carcinogen because it possesses both initiating and tumor promoting activities." (PMID 37097392, 2023). "On ELISA of tumor lysates of core and edge samples, edge lysates demonstrated statistically significant elevations in cytokines TNF-α, IL-1β and IL-6 compared to core lysates." (PMID 37752585, 2023). "We found that three different doses of aconite all increased TNF-α levels in the serum of tumor-bearing mice." (PMID 36756040, 2023). "TNF levels in OC patient serum and ascites are elevated, and existing research suggests the establishment of a “TNF network” that supports tumor progression." (PMID 37298230, 2023). "Other tumor cell‐intrinsic mechanisms of IAPi, when combined with TNF‐α, include enhanced expression of MHC class I and other antigen processing machinery required for the presentation of tumor neoantigens to T cells." (PMID 37132167, 2023). "Treatment of A549 tumor-bearing mice with CA (20 and 40 mg/kg) meaningfully reduced the tumor volume, decreased TNF-α, IL-6, and IL-1β, p-NF-κBp65, and increased Nrf2 and HO-1 in the comparison control group." (PMID 36978983, 2023). "Classically activated macrophages, also termed M1 macrophages, are stimulated by molecules such as LPS, interferon-gamma (IFN-γ), tumor necrosis factor-alpha (TNF-α), and GM-CSF, as well as by target pathogens and tumor cells." (PMID 36831623, 2023). "In peritoneal fluid, the detection of high levels of inflammatory cytokines such as IL-2 and TNF are indicators of tumor cell activity." (PMID 38068912, 2023). "Expression of PD-L1 on tumor cells can be elicited by several factors, but among others, TNF-α and IFN-γ represent the main cytokines able to increase PD-L1 levels in different tumors." (PMID 36854895, 2023). "In the primary tumor, TNFα induces EMT and the expression of IL12Rβ, a subunit of the IL-35 receptor, to promote tumor cell migration and invasion." (PMID 36670988, 2023). "Under in vitro and in vivo (subcutaneous transplantation) conditions, TNFα mediates an increase in tumor growth, and inhibition of the activity of TNFα can lead to a reduction in tumor growth." (PMID 36996146, 2023). "Coculture of TNF-α-pre-stimulated human bone marrow MSCs with MDA tumor cells induced tumor cell apoptosis via the secretion of DKK3, which inhibited the cyclins D1 and D3, and increased P21 expression in the tumor cells." (PMID 36814921, 2023). "Here we provide additional confirmation that TNFα blockade increases anti-tumor immunity and can pair with modalities beyond PD-1 blockade." (PMID 37461742, 2023). "By contrast, studies on cancer or metabolic disorders have focused on disease-specific markers such as tumor weight and tumor necrosis factor (TNF) expression in cancer research." (PMID 37895842, 2023). "Previous studies have shown that TNF had antitumor activity, playing an important role in tumor proliferation, migration, and invasion." (PMID 37704909, 2023). "To further explore the biological function of TNF+ Tregs, we first obtained TNF+ Tregs from gastric cancer tumor tissues of patients by flow cytometry sorting." (PMID 37534250, 2023). "The tumor-suppressing capability of the GPR15-GPR15L axis was associated with a significant influx of CD4+ and CD8+ T cells into the tumor, in particular IFNγ or TNFα secreting T cells." (PMID 38074634, 2023). "Meanwhile, T helper cells secrete various cytokines, including IL-2, TNF-⍺, and IL-12, which enhance natural killer cell-mediated immune responses to exert anti-tumor effects." (PMID 37874419, 2023). "We compared DEX's and TNFα's effects on chemokine expression in two commonly used tumor cell lines (HEK293T and HEPG2) utilizing dual luciferase reporter assays." (PMID 39619227, 2023).
tumor (continued). "Concurrent secretion of interferon gamma (IFN-γ) and tumor necrosis factor (TNF) by cytotoxic CD8+ T lymphocytes leads to a compromise in the integrity of tumor-resident blood vessels, and an ischemic state of the tumor is generated and sustained." (PMID 37345111, 2023). "In the tumor microenvironment, there are different levels of proinflammatory cytokines such as IL-1β, IL-6, IL-8, and TNF-α." (PMID 38137862, 2023). "TNF-α can induce the expression of miRNAs, which leads to increased cell motility and thus enhanced tumor invasiveness by activating extracellular signal-regulated kinase 1/2 (ERK1/2) signaling pathway." (PMID 37233761, 2023). "Birinapant was found to target TRAF2-related cIAP, activate caspase-8 and induce tumor cell death by eliminating TNF-induced NF-κB activation." (PMID 37415241, 2023). "Tumor vasculature is also an important target for cytokines; for example, TNF-α, IL-1, and IL-6 were reported to promote intravascular blood coagulation of small capillaries." (PMID 36839658, 2023). "TNFα is an inflammatory cytokine that has been reported for its anticancer properties through induction of necrosis in certain tumor types and apoptosis in others." (PMID 37331004, 2023). "Murata and colleagues identified prostaglandin D2 as a MC-derived anti-angiogenic factor in expanding solid lung carcinoma that governs the tumor microenvironment by restricting excessive responses to vascular permeability and TNF-α production." (PMID 37686555, 2023). "Macrophages promote tumor angiogenesis and an anti-immune response by emitting TNF-α, vascular endothelial growth factor, and epidermal growth factor, eventually leading to tumor progression." (PMID 37719125, 2023). "Further, neutralization of TNF-α lead to in vivo decreased serum cytokines, inhibited development of invasion, and reduced neutrophils in the tumour microenvironment." (PMID 36980727, 2023). "We explored the colony formation assay in a way analogous to further study of the inhibitory effect of TQ on the tumor growth of TNF-α-activated TNBC cells." (PMID 37373025, 2023). "N1 neutrophils exert a potent inhibitory effect on tumor growth through the production of ROS and TNF-α, concomitant with the downregulation of arginase expression." (PMID 38066437, 2023). "An intracellular cytokine staining of tumor-infiltrating T cells showed that the percentage of Afap1l2-edited OT-I T cells producing TNFα and IFN-γ was twice as high as in controls." (PMID 37388918, 2023). "Yet, with the identification of tumor necrosis factor (TNF) – and the coining of its name – as the factor responsible for exerting the anti-tumor activity of Coley’s toxins and the subsequent cloning of TNF, this concept was reinvigorated." (PMID 36195672, 2023). "The Ki67-labeling index was significantly decreased in the anti-TNFα mAb group, indicating that tumor growth was suppressed by anti-TNFα mAb." (PMID 36996146, 2023). "Tumor necrosis factor (TNF) is an inflammatory cytokine with many biological functions that correlates various types of tumor cells, including cytostatic and cytotoxic effects, differentiation, and proliferation." (PMID 37958804, 2023). "In vivo experiments revealed that HCS1 can promote the infiltration of immune cells into tumor tissues, such as neutrophils, macrophages, and dendritic cells, which further increase the secretion of pro-inflammatory cytokines, such as TNF-α and IL-1β." (PMID 37908720, 2023). "The proliferation and anti-apoptotic potential of tumor cells are also attributed to the elevated levels of IL-6, IL-1b, and TNF-α." (PMID 36840009, 2023). "In tumor tissue with the presence of red blood cells, levels of IL-6, IL-12, IL-1β, and TNF-α are increased." (PMID 37894821, 2023). "The overexpression of TGF-β, TGF-α, EGF, VEGF, and TNF-α promote both survival and tumor proliferation of GBM." (PMID 37190507, 2023).
tumor (continued). "Stimulation of ILKAP KO cells with IFN-γ and TNFα revealed that ILKAP-mediated tumor protection against CTL killing is independent from controlling INF-γ or TNFα sensitivity, changing PD-L1 levels and regulating antigen presentation." (PMID 37732732, 2023). "In the study by Barisas and colleagues, deletion of IL1A from the tumor cells decreased TNFα and total splenic myeloid progenitors." (PMID 37141182, 2023). "OT-I cells with effector-like phenotypes showed greater accumulation in glutamine-treated tumours, and also showed increased T-bet expression and higher frequencies of granzyme B- or IFNγ- and TNF-co-expressing cells." (PMID 37407815, 2023). "TNF α, also referred to as tumor necrosis factor, is a cytokine that possesses the ability to directly eliminate tumor cells, elevated expression levels of inflammatory signatures, and innate immunity." (PMID 37663248, 2023). "Activated NK cells can synthesize and secrete a variety of killing mediators, such as perforin, granzyme B, and TNF-α, which can regulate immunity and directly kill tumor cells." (PMID 36937004, 2023). "Among them, M1-type macrophages under stress have strong antigen-presentation ability and can secrete a large number of pro-inflammatory cytokines, such as TNF-α, IL-6, and IL-12, which have killing effects on tumor cells." (PMID 36903383, 2023). "In vitro studies have demonstrated that butyrate exhibits antitumor effects, such as inhibiting tumor growth by reducing tumor necrosis factor (TNF) secretion in intestinal epithelial cells and inducing differentiation and apoptosis of tumor cells." (PMID 38239850, 2023). "It is assumed that terminally exhausted T cells do not respond sufficiently to PD-1 therapy since they produce lower levels of effector cytokines, such as interferon-γ and tumor necrosis factor-α, and have an attenuated anti-tumor effect." (PMID 37509302, 2023). "In Lewis Lung murine models, knock down of the TNF-α receptor (TNF-R2) in cancer cells promotes robust anti-tumour effects upon administration of low dose murine TNF-alpha, whereas in wild-type mice, it enhanced tumour growth." (PMID 35708739, 2023). "TNF-α-induced NF-κB activation initiates inflammatory pathways, which determine cell survival, death and tumor progression." (PMID 38201482, 2023). "A recent study in EC has demonstrated that polymeric immunoglobulin receptor (pIgR) dependent, antigen-independent IgA occupancy triggers the activation of interferon (IFN) and tumor necrosis factor (TNF) signaling pathway in tumor cells." (PMID 37584707, 2023). "We showed that supernatants collected from AMs with enhanced β-catenin expression led to heightened tumor cell migration and invasion, outcomes characteristic of pro-metastatic behavior, and that anti–TNF-α antibody reduced the extent of migration." (PMID 37092550, 2023). "This is because it is known that loading DCs with tumor cell lysates positively regulates the expression of co-stimulatory surface molecules and increases the secretion of IL-6, IL-12 and TNF-α." (PMID 37048096, 2023). "In this study, we investigated the effects of TNF-α by blocking its action with a monoclonal antibody, Infliximab, and studied the effects on autotaxin secretion and tumor progression." (PMID 38201482, 2023). "Patient studies involving 768 individuals with varying genotypes have shown that TNF-α is a critical player in tumor progression and distant metastasis, especially in TNBC." (PMID 38201482, 2023). "LeY CAR-T cells secrete enhanced levels of IFN-γ, TNFα, and IL-2 with direct stimulation through LeY-expressing tumor targets." (PMID 37371075, 2023). "The tumor blood flow distribution type was significantly correlated with serum TNF-α levels (r = 0.451, P < 0.001)." (PMID 37430251, 2023). "TNF-α, generated by both tumor cells and inflammatory cells within the tumor microenvironment, stimulates the expression of growth factors that facilitate cellular proliferation." (PMID 37772231, 2023).
tumor (continued). "As activated CD4+ and CD8+ T cells would secret TNF-α to exert cytotoxic effects on tumor cells, we performed flow cytometry analysis to detect TNF-α." (PMID 37370831, 2023). "Recent studies have indicated that several cytokines, such as interleukins (ILs), interferons (IFNs), and TNF-α, play important roles in tumor angiogenesis." (PMID 36647777, 2023). "Tumor volumes were reduced when d106S-IL12 treatment was combined with TNFα blockade, leading to significantly enhanced survival in mice." (PMID 37461742, 2023). "Their ability to produce type 1 cytokines (IFNγ, TNFα) as well as cytotoxic effector molecules endows them with potential anti-tumor functions." (PMID 37020559, 2023). "Moreover, it has been previously observed that TNFα is associated with NOx synthesis activity through a variety of pathways, most commonly through the activation of Akt at Ser 473, a signaling pathway involved in several metabolic activities, including tumor growth and insulin resistance." (PMID 36832339, 2023). "In this sense, it has been previously shown that constitutive upregulation of c-MYC and KLF4, as seen in TNF-α + E1 exposed HeLa cells, is associated with CSC enrichment and tumour aggressiveness." (PMID 36674737, 2023). "A TLR3 stimulant packaged in a nanoparticle has been shown to reduce tumor growth by excessive production of TNFα and NO." (PMID 38035101, 2023). "A study demonstrated that proto‐oncogene c‐met (MET), induced by tumor‐derived TNF‐α among other inflammatory stimuli, promotes neutrophil attraction to both primary and metastatic sites." (PMID 38062888, 2023). "Immunohistochemistry and enzyme-linked immunosorbent assay were performed to detect SIRT3 expression and the expression levels of IL-1β, TNF-α, and IL-6, respectively, in tumor tissues." (PMID 37747648, 2023). "For tumour metastasis, subsequent activation of NF-κB, TNF-α and Twist1 is required to modulate the epithelial-mesenchymal transition (EMT)." (PMID 37680708, 2023). "After interfering with the TTR expression of HCCC9810, the tumor cells were co‐cultured with THP‐1 + TNF‐α." (PMID 37688511, 2023). "These events cause a decrease in T cell-mediated anti-tumor immunity and the production of IFN-γ, TNF-α, and IL-2, and it enhances the proliferation of DCs." (PMID 37046762, 2023). "Gratifying anti-tumor effects were achieved in mice injected with TNF-α-pre-stimulated bone marrow MSCs." (PMID 36814921, 2023). "Research has indicated that mast cells can release a substantial amount of TNF-α, which can lead to direct cytotoxicity against tumor cells." (PMID 38155968, 2023). "TNF-α is an important inflammatory cytokine that is a major contributor to tumor progression and is secreted into the tumor microenvironment." (PMID 38202644, 2023). "Adora2b is upregulated on macrophages by IFN-γ and when Adora2b is activated, TNF production in infiltrating macrophages is suppressed, inhibiting their capacity to secrete cytokines important for anti-tumor immunity and promoting tumor growth." (PMID 37187740, 2023). "TNF-α killed tumor cells directly and promoted the formation of cytotoxic lymphocytes and the activity of macrophages." (PMID 37628768, 2023). "Concurrently, a number of TNF-α fusion proteins have been created to guide TNF-α towards tumor tissue by incorporating targeting domains that recognize tumor or tumor-related stromal cell markers." (PMID 37483629, 2023). "Altogether the data show that our tumor‐targeted phage delivery platform has the potential to bring systemic TNFα therapy back to the clinic to treat cancer patients via clinically noninvasive routes (e.g., intravenous)." (PMID 37331004, 2023). "Many stimuli have been reported in the literature, including IFN-γ, GM-CSF, and TNF-α inducing macrophages to M1 polarization for anti-tumor function, and IL-1β, IL-6, IL-10, and IL-4 inducing macrophages to M2 polarization for pro-tumor function." (PMID 37063892, 2023).